AR (androgen receptor)
Diseases named in the same sentence as AR in open-access papers (continued):
Sharing a sentence is not in itself a finding about the gene and the disease.
prostate carcinoma (continued). "In AR‐overexpressing VCaP (prostate cancer) cells, conversely to enzalutamide, TAS3681 effectively suppressed cell proliferation and downregulated AR expression." (PMID 38600681, 2024). "The main protein that drives prostate cancer (PC) growth and progression is the androgen receptor (AR), a transcription factor induced by androgenic steroids (e.g., testosterone) to regulate the genetic network supporting PC growth." (PMID 38416822, 2024). "The antagonism of RORγ can effectively inhibit AR expression and impede prostate cancer growth, underscoring the critical role of stable RORγ expression in prostate cancer progression." (PMID 39771106, 2024). "In the tumor microenvironment, particularly in cancers such as prostate cancer, AR signaling can inhibit NF-κB activity to exert anti-inflammatory effects, while NF-κB activation can suppress AR signaling, promoting cell survival and growth." (PMID 39335190, 2024). "Remarkably, unlike GNE-049, one hour pre-treatment with CBPD-409 completely attenuated ligand-induced transcriptional activity of AR in prostate cancer cells." (PMID 38586029, 2024). "We transiently expressed ID2 in a panel of prostate cancer cell lines; Western blot analysis showed decreased expression of AR and PSA in LNCAP cells, while the expression of NE markers such as CHGA, ENO2, and SYP was elevated in both LNCAP and PC3 cells." (PMID 38254880, 2024). "Accumulating evidence suggests that androgen receptor (AR)-mediated signaling plays an important role in the development and progression of prostate cancer." (PMID 38474045, 2024). "It is reported that AR regulates p21 expression in prostate cancer due to the existence of androgen response elements (ARE) in the promoter region of p21." (PMID 38605607, 2024). "Our finding provided new knowledge for understanding how androgen determines the dual roles of AR on prostate cancer metastasis." (PMID 39149855, 2024). "The dependence of prostate cancer on androgen biology and its role in disease progression and metastasis makes targeting AR signalling a cornerstone of prostate cancer therapeutic intervention." (PMID 39858418, 2024). "The mechanisms by which prostate cancers acquire this resistance are well characterized, with AR signaling being integral to many of them." (PMID 38542265, 2024). "Concordantly, a dual NSD1/2 PROTAC degrader, called LLC0150, was preferentially cytotoxic in AR-dependent prostate cancer as well as NSD2-altered hematologic malignancies." (PMID 38464251, 2024). "Taken together, these findings demonstrate that WAM induces apoptosis via the ROS-mediated inhibition of HSP27 and the androgen receptor in prostate cancer." (PMID 38474045, 2024). "Just like the androgen receptor (AR), the estrogen receptor α (ERα) is expressed in the prostate and is thought to influence prostate cancer (PCa) biology." (PMID 38625747, 2024). "The intricate landscape of prostate cancer progression, marked by the emergence of AR-Vs, has prompted an intensive exploration of novel therapeutic approaches to tackle the challenges posed by these variants." (PMID 38201308, 2024). "Using targeted DMS-MaPseq we determined the RNA secondary structure landscape of two low abundance transcripts, AR FL and V7, in 22Rv1 prostate cancer cells." (PMID 38554103, 2024). "For example, an over-activation of the androgen receptor in prostate cancer cells suppresses the transcriptional expression of TβRII by suppressing the interaction of SP1 with the TβRII promoter." (PMID 38675493, 2024). "The androgen receptor (AR) is a primary target for treating prostate cancer (PCa), forming the bedrock of its clinical management." (PMID 38564048, 2024). "YAP1 acts synergistically with AR to shift prostate cancer from androgen-dependent to castration-resistant growth." (PMID 38887275, 2024).
prostate carcinoma (continued). "The membrane protease known as prostate specific membrane antigen (PSMA) is usually found in abundance on the surface of prostate cancer cells, and androgen receptor expression is intimately related to proliferation of cancer cells." (PMID 38637848, 2024). "Previous studies suggested a stimulating role of androgen receptor (AR) on prostate cancer (PCa) metastasis." (PMID 39149855, 2024). "This, in turn, suggests that a crucial pivot for overcoming the inefficacy of AR inhibitor combined with immunotherapy in prostate cancer lies in restoring the mitochondrial function of T cells." (PMID 39247809, 2024). "The treatment of prostate cancer is based on androgen deprivation and inhibition of the testosterone/androgen receptor axis [androgen receptor axis inhibitors (ARPI)]." (PMID 39481329, 2024). "We next assessed the effects of LPHN ligands on the expression of LPHNs, as well as AR, in prostate cancer cells." (PMID 39000396, 2024). "The seminal discovery by Charles Huggins and Clarence Hodges in the 1940s, demonstrating tumor regression after androgen deprivation, laid the foundation for targeting AR in prostate cancer therapy." (PMID 39335158, 2024). "Background/Objectives: Androgen receptor (AR) expression and signaling are critical for the progression of prostate cancer and have been the therapeutic focus of prostate cancer for over 50 years." (PMID 39591176, 2024). "Collectively, these findings indicate that BWA-522 is an orally bioavailable degrader targeting the AR-NTD with the potential for clinical application in prostate cancer therapy." (PMID 38675453, 2024). "Recent studies have revealed that the functional target of BET proteins varies in different types of cancer 15-17; for example, p21 is the target in NSCLC 18, and AR is the target in prostate cancer." (PMID 38169595, 2024). "We simulated transcriptional alterations that arise from prolonged AR inhibition in prostate cancer and compared these alterations between AA and EA men." (PMID 38566104, 2024). "The cytotoxicity of DIM and BIMs in general extends to other types of cancers as well, such as prostate cancer by being an androgen receptor (AR) agonist in LNCaP prostate cancer cells." (PMID 38410780, 2024). "It has been shown that CP promotes prostate cancer development by enhancing AR expression (Zhang Z.-B." (PMID 38803438, 2024). "Most prostate cancers are sensitive to androgens, the androgen receptor (AR) is upregulated, producing a stimulating effect on the growth and progression of cancer cells." (PMID 38291502, 2024). "Of note, PAK6 expression is upregulated in a number of cancers and PAK6 interaction with androgen receptor (AR) promotes its phosphorylation and prostate cancer cell motility and invasion." (PMID 39419978, 2024). "In AR-positive prostate cancer cells, CREB5 interacts with and enhances FOXA1 and AR activity thereby regulating a subset of targets such as MYC and genes related to cell cycle, Wnt signaling and EMT." (PMID 38233872, 2024). "Among body tissues or pathologies, AR signaling is most comprehensively investigated in prostate cancer, where it is the key oncogenic driver." (PMID 38317241, 2024). "HDAC overexpression in prostate cancer, which is crucial for functional androgen receptor signaling, suggests their influential role in PMN-MDSC and M-MDSC dynamics within mCRPC." (PMID 38887300, 2024). "The genome-wide distribution profiles of H2BK5ac and H2BK20ac in prostate cancer cells further confirmed a specific enrichment of H2BNTac at AR/p300 co-bound enhancers." (PMID 38586029, 2024). "Our recent study showed that the reduced CMG2 expression in both breast and prostate cancers can be a result of repression mediated by ER and AR." (PMID 39199664, 2024). "The lncRNA CCAT1 can deteriorate prostate cancer to denervation-resistant prostate cancer by binding to intracellular miR-28-5p, thereby altering androgen receptor co-activators and affecting the AR signaling pathway." (PMID 38605206, 2024).
prostate carcinoma (continued). "Combined with increased phospho-SHP2 and progressive loss of pY54-H3 in patients, these results establish a crucial role for ACK1/SHP2/pY54-H3/AR signaling in prostate cancer pathogenesis." (PMID 38965223, 2024). "The androgen receptor (AR) is critical in driving prostate cancer (PCa) development, with androgen deprivation therapy (ADT) being the standard treatment for PCa patients." (PMID 38687617, 2024). "Prostate cancer cells are initially reliant on circulating androgens to activate endogenous androgen receptor (AR)." (PMID 37904926, 2024). "To determine the effects of HDACi on prostate cancer cell migration, we performed migration assays in AR-positive LNCaP cells using several concentrations of SAHA (0.1, 0.25, 0.5, 1, 2 and 4 μM), a commercially available HDACi." (PMID 38254786, 2024). "In prostate cancer from AA men, genes including known AR target genes TRIM63, ATP2A1, and ARHGAP28, showed a significant inverse correlation between gene expression and DNA methylation." (PMID 38566104, 2024). "UBX‐390 degrades AR in prostate cancer cells via the ubiquitin‐proteasome system and suppresses AR‐related gene expression, thereby inhibiting the AR signaling pathway." (PMID 38958553, 2024). "Using AR+ LNCaP cells as a prostate cancer (PCa) model, Torin2 and XAV939 treatment for 3 days disturbed the expression of 10 and 6 out of 12 integrin genes, respectively." (PMID 39436262, 2024). "In the current study, the apoptotic mechanism of water extract from Astragalus membranaceus (WAM) was examined in LNCaP prostate cancer cells in association with ROS-mediated HSP27 and AR signaling." (PMID 38474045, 2024). "A recent study identified the master regulator of lysosomal biogenesis, the lysosome associated transcription factor EB (TFEB), which is a transcriptional target of the androgen receptor (AR) in prostate cancer." (PMID 39217195, 2024). "The overall results observed in the current study support the efficacy of the synthesized analogs of androgen receptor blockers as potential anticancer drugs in the treatment of prostate cancer tumors." (PMID 39062524, 2024). "The importance of AR in human physiology becomes particularly evident in prostate cancer (PCa) where aberrant AR signaling emerges as a critical driver of tumorigenesis." (PMID 38030789, 2024). "There are 770 DEGs found to be regulated by AR in prostate cancer through intersecting AR Chip-seq data from the SRA and TCGA databases." (PMID 38778150, 2024). "Activation of FKBP5 transcription via the androgen receptor (AR) was reported in prostate cancer and via the GR in human lung cancer A549 cells." (PMID 38786025, 2024). "We began by examining the effects of cisplatin and of 14 azolato-bridgedcomplexes (0–50 μM) on the viability of LNCaP cells,an AR-positive prostate cancer cell line." (PMID 39258898, 2024). "Compound 40 was found to exhibit down-regulation of AR-regulated transcription and suppressed expression of AR-regulated proteins in androgen-dependent prostate cancer cells, 22Rv1-ARE14 and VCaP." (PMID 39598525, 2024). "The initiation of ADT marks the beginning of treatment for castration-naive prostate cancer (CNPC), with the addition of an androgen receptor pathway inhibitor (ARPI) for patients with metastatic castration naive prostate cancer (mCNPC)." (PMID 39692806, 2024). "Primary prostate cancer (PCa) development is predominantly driven by androgens acting through its cognate binding partner, the androgen receptor (AR), and consequently led to the use of androgen-deprivation therapy (ADT) as the standard care regimen for PCa." (PMID 38739593, 2024). "This is particularly relevant in the context of prostate cancer, where Kdm3a regulates the transcriptional program of AR, facilitating tumor growth and progression." (PMID 39857659, 2024).
prostate carcinoma (continued). "Here, WAM suppressed the expression of the AR and PSA and inhibited DHT-induced PSA and AR expression in LNCaP cells, implying that WAM inhibits ligand-dependent AR signaling leading to apoptosis in prostate cancer." (PMID 38474045, 2024). "Enzalutamide is a second-generation antiandrogen with improved affinity for AR and increases the survival of prostate cancer patients compared to bicalutamide." (PMID 38339092, 2024). "With the advent of updated androgen receptor (AR)-targeted drugs, the metastatic castration-resistant prostate cancer (mCRPC) treatment tactics have been influenced significantly." (PMID 38898958, 2024). "Enzalutamide (ENZ), marketed under the brand name Xtandi® as a soft capsule, is an androgen receptor signaling inhibitor drug actively used in clinical settings for treating prostate cancer." (PMID 38675118, 2024). "Inhibition of EP300/CREBBP’s acetyltransferase disrupts the transcriptional activity of both AR and GR in prostate cancer cells." (PMID 39027480, 2024). "Androgens drive prostate cancer cell growth through the androgen receptor (AR), which depends on HSP90 for survival and progression." (PMID 38339390, 2024). "Previous studies have shown that FoxO1 inhibits the androgen-independent activation of AR in prostate cancer." (PMID 39075471, 2024). "Treatment-induced neuroendocrine prostate cancer (t-NEPC) is a lethal subtype of castration-resistant prostate cancer resistant to androgen receptor (AR) inhibitors." (PMID 38238517, 2024). "ZWINT is a target of AR which is upregulated in PCa, and it has been also identified with bioinformatics tools as a hub gene in prostate cancer." (PMID 38542079, 2024). "This is further affirmed by the FDA’s recent approval of three second-generation AR antagonists for patients at different stages of prostate cancer since 2012." (PMID 38339414, 2024). "Anti-androgens, such as bicalutamide, nilutamide, flutamide, enzalutamide, apalutamide and darolutamide, work by blocking androgen receptor (AR) in prostate cancer cells." (PMID 38254786, 2024). "Honokiol treatment reduces AR protein levels in both androgen-responsive and androgen-independent prostate cancer cells through proteasomal degradation and decreased AR mRNA levels." (PMID 39199550, 2024). "Continued exploration of the androgen receptor (AR) is crucial, as it plays pivotal roles in diverse diseases such as prostate cancer (PCa), serving as a significant therapeutic focus." (PMID 39014480, 2024). "Collectively, these data suggest that one mode of action of CDKI-73 is to reduce AR expression and activity in prostate cancer cells." (PMID 39117800, 2024). "CtDNA was detected using targeted NGS in 102 patients with Stage IV castration-resistant prostate cancer treated with abiraterone, an inhibitor of androgen receptor (AR) signaling." (PMID 38791958, 2024). "In prostate cancer, the androgen receptor (AR) plays a vital role in the growth of prostate cancer and castration-resistant prostate cancer." (PMID 39482529, 2024). "To investigate the effectof 5-H-Y on prostate cancer cell proliferation via AR signaling, we evaluated the mRNA expression levelsof the AR-responsive genes encoding PSA and transmembrane protease,serine 2 (TMPRSS2) after 5-H-Y treatment in LNCaP cells." (PMID 39258898, 2024). "Degradation of unliganded androgen receptor (AR) in prostate cancer cells can be prevented by proteasome inhibition, but this is associated with only modest increases in polyubiquitylated AR." (PMID 38182874, 2024). "The therapy effectively suppresses testosterone and disrupts its action, thereby inhibiting the androgen receptor (AR) pathway that drives prostate cancer progression." (PMID 39200727, 2024). "The role of AR is well-proved in organ malignancies such as prostate cancer, breast cancer, pancreas cancer and ovarian cancer." (PMID 39083104, 2024).
prostate carcinoma (continued). "5hmC-sequencing in cfDNA identified a subgroup of prostate cancer patients with preexisting activation (5hmC hypermethylation) of gene sets involving AR, FOXA1 and GRHL2 before initiating ADT." (PMID 37904926, 2024). "This study assessed the effects of UBX‐390, a novel cereblon (CRBN)‐based AR degrader, on prostate cancer cells." (PMID 38958553, 2024). "Resistance of the prostate cancer cells LNCaP to the AR inhibitor apalutamide is linked to TLE3 loss, and this is also the case for resistance to enzalutamide, a structurally close AR inhibitor, as shown in subsequent validation experiments." (PMID 38255778, 2024). "PIAS4 with transcriptional co-repressor of androgen receptor interacts with DNA-binding domain of the AR that is essential for prostate cancer development and progression." (PMID 38590645, 2024). "In the present study, we demonstrated that androgen considerably induced the expression of not only LPHN3 but also LPHN1 and LPHN2 in AR-positive prostate cancer cells, which was at least partially blocked by an anti-androgen." (PMID 39000396, 2024). "By targeting AR signaling pathways, honokiol impairs AR-mediated transcriptional activity, enhancing the efficacy of existing prostate cancer therapies and offering potential applications for treating castration-resistant prostate cancer (CRPC)." (PMID 39199550, 2024). "The heat shock protein 70 inhibitor VER155008 suppresses the expression of HSP27, HOP and HSP90β and the androgen receptor, induces apoptosis, and attenuates prostate cancer cell growth." (PMID 39668827, 2024). "Antineoplastic therapies for prostate cancer (PCa) have traditionally centered around the androgen receptor (AR) pathway, which has demonstrated a significant role in oncogenesis." (PMID 38396837, 2024). "Current treatments for prostate cancer use androgen receptor signaling and combination therapy with two or three ADT drugs." (PMID 38255288, 2024). "Inhibition or overexpression of miR-1271–5p levels affects prostate cancer cell growth, apoptosis and expression of both androgen receptor target genes and other genes that are likely direct targets, dependent on androgen receptor status, and tumour stage." (PMID 39267821, 2024). "MYSM1 co-activates androgen receptor (AR) action to promote prostate cancer, while MYSM1 inhibits castration-resistant prostate cancer (CRPC) process through PI3K/Akt signaling regulation." (PMID 38177530, 2024). "Here, we demonstrate that p300/CBP are determinant cofactors of the active AR enhanceosome in prostate cancer." (PMID 38586029, 2024). "The evolved AR‐Vs lack ligand‐binding domain (LBD) and are constitutively active, driving androgen‐independent AR transcription, and is critical in developing treatment‐resistant prostate cancer." (PMID 38605607, 2024). "Men with prostate cancer receive AR-targeted therapies for prolonged periods, usually until the disease relapses." (PMID 38566104, 2024). "Overall, we find p300/CBP degradation using CBPD-409 to be a potent therapeutic strategy with high selectivity to prevent cell growth of AR-positive prostate cancer." (PMID 38586029, 2024). "The new study seems to provide a new insight into AR-targeted therapy from an immunological perspective, which is a win–win event for both prostate cancer treatment and tumor immunotherapy." (PMID 38254871, 2024). "Since the aberrant and persistent AR signaling drives the prostate cancer (PCa) development and progression, the receptor is the main precision target of cancer therapy." (PMID 38015476, 2024). "In this study, we identified CTBP2 as a candidate AR/OCT1 target gene and showed that it is associated with prognosis of prostate cancer." (PMID 38698344, 2024). "In prostate cancer (PCa), androgens upregulate tumorigenesis, whereas in benign tissue, the revival of androgen receptor (AR) signaling suppresses aggressive behaviors, suggesting therapeutic potential." (PMID 39201315, 2024).